TNF (tumor necrosis factor)
Diseases named in the same sentence as TNF in open-access papers (continued):
Sharing a sentence is not in itself a finding about the gene and the disease.
influenza (continued). "Furthermore, we found that CD8+ T-cell-specific inhibition of TNF-α processing did not impair host protection against influenza virus as influenza-specific ADAM17−/− CD8+ T cells were able to provide complete protection against an otherwise lethal viral challenge." (PMID 24223177, 2013). "This suggests that inhibition of TNF-α processing may also lessen disease severity without compromising the immune response against the virus, and introduces a new target to limit pulmonary pathology during influenza infection." (PMID 24223177, 2013). "Theses studies describe a critical role for TNF-α processing by CD8+ T cells in the initiation and severity of acute lung injury, which may have important implications for limiting immunopathology during influenza infection and other human infectious or inflammatory diseases." (PMID 24223177, 2013). "We found that TNF, IL-6, and MCP-1 were not significantly different in Tpl2-inhibited influenza-infected cells compared to vehicle-treated influenza-infected controls." (PMID 35051238, 2022). "Following stimulation with influenza antigens, CD4+ TRM T cells produced TNF-α in all vaccinated groups but not in the unvaccinated group." (PMID 33497364, 2021). "During the interview, one of the pulmonologists stated, “Before (Anti-TNF) initiation, we assess the patient’s schedule for vaccination because most patients, regardless of whether we are giving them infliximab or not, are keen to start the pneumococcal and influenza vaccines." (PMID 31584996, 2019). "It was interesting that protein amounts of the pro-inflammatory cytokines TNF-α, MIP-2, GM-CSF and IFN-γ in BALF were generally higher at both time points in BALF of smoke alone versus no treatment mice or smoke and influenza mice." (PMID 18627612, 2008). "In contrast to anti TNF agents, IBD patients being treated with vedolizumab vaccine efficiency seem to not be affected after vaccination against influenza and hepatitis B, possibly due to its selective mechanism of action as antibody against the α4β7 integrin, which is mainly expressed in the gut." (PMID 35052849, 2022). "Hence, the influenza-induced alteration in cDC differentiation is independent of IFN-γ, type I IFNs, TNF-α, and IL-6." (PMID 30372491, 2018). "A recent report in children with juvenile idiopathic arthritis (JIA) vaccinated against pandemic influenza showed that the antibody response overall was lower in patients with JIA, but neither MTX nor anti-TNF remedies affected the immune response significantly." (PMID 24383620, 2014). "In the context of influenza infection, despite no changes in the absolute numbers of CD8+ T cells in the airways in the absence of NKG2A, we observed increased levels of effector CD8+ T cell cytokines, such as TNF-α." (PMID 25251060, 2014). "TNF-α and GM-CSF proteins were absent or present in low amounts in BALF of influenza infected mice, except for smoke and influenza mice at d10, which may reflect production by macrophages and lymphocytes." (PMID 18627612, 2008). "In a comparison of immune responses to influenza vaccination in RA patients treated with different DMARDs, it was observed that patients treated with MTX alone had a more robust antibody titer for influenza antigens than patients treated with TNF-alpha blockers with or without MTX." (PMID 40281592, 2025). "Additionally, SARS-CoV-2 can increase pro-inflammatory cytokines, including interleukin (IL)-2, IL-6, IL-7, and tumor necrosis factor-alpha (TNF-a), to levels not typically seen in bacterial sepsis or influenza and contribute to thrombosis formation via multiple mechanisms." (PMID 38903348, 2024). "Similarly, human peripheral blood mononuclear cells isolated from H1N1 influenza infected patients failed to generate adequate TNF-α and IFN-γ levels upon exposure to S. pneumoniae, signifying a vulnerability of influenza infected persons to pneumococcal superinfection." (PMID 23483993, 2013).
influenza (continued). "Since the threat of new influenza pandemics is a constant and CD8 T cells are important in controlling influenza infection when neutralizing antibody responses are absent, the need to understand the impact of TNF signaling in influenza infection is particularly important." (PMID 23874808, 2013).
Hepatic steatosis (439 papers, 2008 to 2026). Steatosis is a term used to denote lipid accumulation within hepatocytes. "Hepatic steatosis is closely associated with chronic low-grade inflammation, characterized by elevated pro-inflammatory cytokines such as TNF-α, IL-6, and C-reactive protein." (PMID 40502403, 2025). "In high-fat diet-induced hepatic steatosis, Kupffer cells polarize toward M1, producing pro-inflammatory cytokines such as Interleukin-1 (IL-1), Interleukin-6 (IL-6), tumor necrosis factor α (TumorNecrosisFactor-α, TNF-α), causing inflammation." (PMID 40650120, 2025). "These activated T cells exhibited increased TNF-α expression (2- and 1.9-fold, respectively; both p < 0.01), associated with liver steatosis, inflammation, and hepatocyte ballooning." (PMID 40362271, 2025). "HC has been documented to induce fatty liver disease, while high-galactose consumption is associated with severe oxidative stress, senescence, and efflux of pro-inflammatory cytokines, such as TNF-α, IL-6, and IL-10, in the liver." (PMID 41462653, 2025). "The production of tumor necrosis factor -alpha (TNFα) has been associated with fatty liver disease (i.e, hepatosteatosis) for many years." (PMID 40766326, 2025). "Research suggests that exposure stimulates the production of pro-inflammatory cytokines, such as TNF-α, linked to inflammatory liver conditions like fatty liver disease." (PMID 39858783, 2024). "LPS binds to Toll-like receptor 4 on the surface of hepatic Kupffer cells and activates the NF-κB-mediated TNF-α signaling pathway, causing hepatic steatosis and inflammation." (PMID 38126998, 2023). "p38α-deficiency in macrophages resulted in attenuated hepatic steatosis, due to reduced secretion of pro-inflammatory cytokines (TNF-α, CXCL10 and IL-6)." (PMID 36845555, 2023). "Chronic HCV infection is associated with increased levels of TNFα, and elevated TNFα levels are associated with increased liver pathology from fatty liver to hepatocellular carcinoma." (PMID 36423130, 2022). "Tumor necrosis factor -alpha (TNFα) is strongly associated with fatty liver disease (i.e, hepatosteatosis)." (PMID 36865784, 2022). "Tumor necrosis factor α (TNFA) has been shown to be strongly associated with fatty liver in dairy cows in vivo and palmitate is the primary fatty acid found in circulation of dairy cows with fatty liver." (PMID 36465509, 2022). "CD18 mutants did exhibit increased IL-1 and TNF gene expression in the liver, which has been linked to hepatic steatosis." (PMID 28873429, 2017). "Fatty liver disease is associated with increased TNF-α levels and decreased adiponectin levels, phenomena that correlate with inflammation and fibrosis severity." (PMID 28570676, 2017). "Next, we examined the expression of genes involved in β-oxidation, the TNFα signaling pathway and hypoxia, all of which have been associated with alcohol-induced hepatic steatosis." (PMID 27562099, 2016). "Hepatic steatosis is associated with increased expression of TNFα, which stimulates lipogenesis and lipolysis as well as inducing hepatic dysfunction." (PMID 25057104, 2014). "Another study reports that hepatic steatosis was significantly improved and associated to a decreased TNF-α production in rats treated with resveratrol." (PMID 25937854, 2014). "This in turn promotes hepatic steatosis and inflammation through the production of pro-inflammatory cytokines, such as tumor necrosis factor (TNF)-α and interleukin (IL)-6, and is closely associated with liver carcinogenesis." (PMID 21711565, 2011). "Moreover, a high amount of circulating TNFα has been linked to MAFLD severity while TNFα signaling inhibition lowers liver steatosis and hepatocellular injury in MAFLD mouse model." (PMID 37620891, 2023). "The necroinflammatory form of non-alcoholic hepatic steatosis might be implicated in cardiac dysfunctions through the release of different proinflammatory cytokines (C-reactive protein, IL-6, and TNF-α) with consequent cardiac alterations." (PMID 36211332, 2022).
Hepatic steatosis (continued). "The promotion of hepatic steatosis resulting from perforin deficiency was associated with a strong increase in hepatic macrophage accumulation and inflammation as evaluated by the expression of TNF-α, IL-6, and iNOS." (PMID 32528465, 2020). "Therefore, maladaptive processes implicated in hepatic steatosis and liver inflammation are associated with the central effects of TNF on insulin dysregulation." (PMID 31892368, 2019). "Additionally, increases in the level of TNF-α were observed in the blood circulation and liver tissues of hepatic steatosis patients, which indicate that it is closely associated with disease severity and morbidity." (PMID 31001563, 2019). "Meanwhile, our study suggests that restoration of systemic and intestinal vitamin D deficiency using by chronic vitamin D treatment effectively reduces TNFα-mediated immunological abnormalities associated with the gut-adipose tissue-liver axis and hepatic steatosis in NASH rats." (PMID 29684027, 2018). "In this study, the SGR was associated with the decreased TG synthesis and prevention of alcoholic fatty liver in mice, caused by the inhibition of TNF-α and mature SREBP-1c, stimulation of PPAR-α expression, and AMPK phosphorylation as well as the enhancement of serum adiponectin level." (PMID 26101535, 2015). "Consequently, oxidative stress causes the release of several cytokines, including TNF-α, a critical cytokine in hepatic steatosis development, by Kupffer cells." (PMID 23691094, 2013). "These could possibly determine TNFα mediated alterations mainly the phenotypes of hepatic steatosis and fatty liver associated with several hepatic pathological states." (PMID 20140224, 2010). "Interestingly, they found that the incidence of steatohepatitis was correlated with serum levels of the inflammatory markers monocyte chemoattractant protein (MCP), TNF-α, and IL-1β, which highlights the association between systemic inflammatory status and fatty liver." (PMID 37434233, 2023). "Furthermore, inflammatory cytokines, especially TNF-α, and Rubicon may be associated with the development of hepatic steatosis." (PMID 33388967, 2021). "Moreover, as serum AC16:0 and AC18:1 are reported to be positively correlated with TNFα and IL-6 and associated with fatty liver disease, these changes may indicate inflammation and poor metabolic health in the underweight women." (PMID 33201881, 2020). "TNFα SNPs have been reported to influence susceptibility to several hepatic diseases including alcoholic steatohepatitis as TNFα appears to be involved in both the early stage of fatty liver disease and also the transition to steatohepatitis and more advanced stages of liver damage." (PMID 23394097, 2013). "Among NAFLD populations, some trials have demonstrated that TRE improves body weight, body fat, inflammatory markers (such as hs-CRP and TNF-α), and liver-related assessments (including hepatic steatosis, liver fibrosis, and liver enzyme levels)." (PMID 41601725, 2026). "The levels of pro-inflammatory markers, such as IL-6, IL-1β, and TNF-α, were significantly reduced after EA administration, confirming the compound's ability to mitigate hepatic steatosis and inflammation in a dose-responsive manner." (PMID 41530836, 2026). "Upon entering the circulation, LPS first targets the liver and induces the overexpression of tumor necrosis factor-alpha (TNF-α) and chemokines, which in turn promote neutrophil infiltration, hepatocellular injury, and hepatic steatosis." (PMID 41488302, 2025). "Hepatic steatosis and excess visceral adiposity promote the release of pro-inflammatory cytokines—most notably tumor necrosis factor-alpha (TNF-α), interleukin-6 (IL-6), and interleukin-1β (IL-1β)—which exert deleterious effects on musculoskeletal tissues." (PMID 41458554, 2025). "Histological analysis was performed to evaluate hepatic steatosis, fibrosis, as well as the levels of inflammatory cytokines (IL-6, TNF-α) and antioxidant markers (SOD, GSH)." (PMID 40717987, 2025).
Hepatic steatosis (continued). "Significant evidence suggests that inflammation, driven by elevated levels of serum tumor necrosis factor-α (TNF-α) and interleukin 6 (IL-6), is a crucial mechanism in high-fat diet-induced fatty liver and determines the severity of the condition." (PMID 40141836, 2025). "TNF-α is a pro-inflammatory cytokine mainly produced by macrophages and monocytes, which can lead to a series of problems such as hepatic steatosis, inflammatory cytokine infiltration and hepatocyte necrosis." (PMID 39861457, 2025). "TNF-α significantly exacerbates hepatic steatosis, while IL-6 potently activates lipogenic factors in hepatocytes." (PMID 40098962, 2025). "This inflammation, marked by imbalanced TNF-α, IL-6, adiponectin, and leptin, promotes hepatic steatosis and IR, a core NAFLD pathogenesis." (PMID 41334428, 2025). "The liver communicates with pancreatic β-cells via hepatokines (e.g., fetuin-A, selenoprotein P) and inflammatory cytokines (e.g., IL-6, TNF-α) that are elevated in hepatic steatosis." (PMID 40691629, 2025). "Serum fetuin-B has been shown in clinical investigations to be favorably correlated with indicators of adipose tissue inflammation, including IL-6 and TNF-α, as well as the degree of hepatic steatosis." (PMID 40868109, 2025). "Reduces body weight, decreases visceral fat mass, improves serum lipid profile (reduces cholesterol, NEFA, TNF-α), decreases liver lipid accumulation, improves hepatic steatosis, and lowers insulin levels." (PMID 39963239, 2025). "In dietary supplementation models, spermidine has been shown to enhance autophagic flux, reduce hepatic steatosis, and suppress the expression of pro-inflammatory cytokines, such as TNF-α and IL-1β, thereby mitigating liver injury and fibrosis." (PMID 40647314, 2025). "Reduced expression of hepatic inflammatory cytokines (TNF-α, IL-1β, IL-18) and improved hepatic steatosis; decrease in body weight as well." (PMID 40893881, 2025). "Collectively, these findings suggest that STING mediates liver steatosis, fibrosis, and inflammation through promoting NF-κB activation and subsequent TNF-α and IL-6 production in KCs." (PMID 40098962, 2025). "On the contrary, the current study also determined the expression level of TNF-α, an inflammatory response reported to play a crucial crosslinking role in the development of fatty liver." (PMID 40730505, 2025). "Evidence for the participation of TNFα in fatty liver disease is overwhelming, although direct evidence from animal models has been mixed." (PMID 40766326, 2025). "It has been shown that ellagic acid can significantly down-regulate the levels of liver inflammatory factors NF-κB, TNF-α, IL-1β, and IL-6 in mice with fatty liver disease induced by AKT gene transfection." (PMID 39877634, 2025). "In support of our observations, an increase in Firmicutes contributed to the development of hepatic steatosis and elevation of TNF-α mRNA levels, and an elevated ratio of Firmicutes/Bacteroidetes was linked to inflammation and oxidative stress." (PMID 39338312, 2024). "TNF-α plays a role in developing hepatic steatosis but mainly in the progression of the disease to hepatic inflammation and fibrosis, as it is reviewed in detail elsewhere." (PMID 38459229, 2024). "TNF-α levels positively correlated to the severity of liver disease, and TNFR1 deficiency exerts a protective effect against hepatic steatosis and liver damage." (PMID 39244571, 2024). "Adenovirus-mediated overexpression of GR (subtype β) resulted, apart from the development of hepatic steatosis, in the increase in tumor-necrosis factor-α (TNF-α) and activation of its downstream signaling, nuclear factor-kappaB (NF-kB), in HFD-treated mice." (PMID 38459229, 2024). "When we fed KAL-Tg mice and wild-type (WT) mice with HFD, KAL-Tg mice exhibited extensive inflammation, injury, and fibrosis along with aggravated hepatic steatosis, and the expression of TNFα, interleukin-6 (IL-6), α-SMA, and collagen I was also increased." (PMID 38472195, 2024).